MYC (MYC proto-oncogene, bHLH transcription factor)
Diseases named in the same sentence as MYC in open-access papers (continued):
Sharing a sentence is not in itself a finding about the gene and the disease.
colorectal cancer (continued). "In conclusion, CDH17 plays a crucial role in maintaining colorectal cancer cell stemness and chemoresistance via LGR5/Wnt/MYC signaling and SLC38A5 expression." (PMID 40595509, 2025). "For example, we used stat-FISH to investigate H716, a colorectal cancer cell line where interSeg predicted EC-amp for two distinct probes, corresponding to FGFR2 and MYC, for each investigated cell." (PMID 40667255, 2025). "In HCT116 colorectal cancer cells, MYC expression was found to increase, while c-Myc protein translation occurred at a level comparable to that in healthy cells." (PMID 40226330, 2025). "To investigate ecDNA replication, we used the colorectal cancer cell line COLO 320DM, which carries an amplification of the c-MYC locus on multiple ecDNAs." (PMID 40744497, 2025). "In colorectal cancer, knockdown of IGF2BP2 attenuates MYC-mediated glycolysis in colorectal cancer cells, and the LINRIS–IGF2BP2–MYC axis is a promising therapeutic target for colorectal cancer." (PMID 40469197, 2025). "Through a meticulous exploration involving enrichment analysis and pathway analysis, this research aims to shed light on the intricate roles played by MYC and NCAPG2 in the development of colorectal cancer." (PMID 38637125, 2024). "For instance, in colorectal cancer, CREB1 activates MYC through lncRNA CCAT1, primarily promoting cell proliferation without affecting the regulation of integrin proteins and their associated suppression of metastasis." (PMID 39883338, 2024). "With YAP1 activation, BIRC3/5 and MYC are the downstream targets of YAP1 under specific conditions, such as in cystic kidney epithelium and colorectal cancer cells." (PMID 38730465, 2024). "In particular, MYC, MAD2L1, CENPF, UBE2C, NUF2 and NCAPG2 were identified as highly expressed in colorectal cancer samples." (PMID 38637125, 2024). "The elevated expression of MYC and NCAPG2 in colorectal cancer is one of the key findings of this study." (PMID 38637125, 2024). "Using the online database, we also found that HDAC6 was positively correlated with the downstream target genes of STAT1 or NF-κB p65, such as MYC, RELA (p65) and BCL2L1, in colorectal cancer specimens." (PMID 38231305, 2024). "We then examined the expression levels of c-MYC and its downstream genes (GLUT1 and CDK4) in colorectal cancer cells ectopically expressing STK16 or sgSTK16." (PMID 38622518, 2024). "In many cases of colorectal cancer, there is a considerable increase in the production of the MYC gene, resulting in an overabundance of its protein product (c-MYC)." (PMID 38637125, 2024). "High expression of MYC and NCAPG2 is significantly predictive of clinical outcomes in colorectal cancer patients, indicating their potential clinical relevance." (PMID 38637125, 2024). "To further investigate the relationship between STK16 and c-MYC, we generated four types of colorectal cancer cells stably expressing vector + shnc, STK16 + shnc, STK16 + shc-MYC#1, STK16 + shc-MYC#2 using lentivirus." (PMID 38622518, 2024). "The core genes, namely MYC, MAD2L1, CENPF, UBE2C, NUF2 and NCAPG2, showed elevated expression in colorectal cancer samples, in stark contrast to their comparatively lower expression in normal samples." (PMID 38637125, 2024). "In colorectal cancer, the expression of HDAC6 was significantly positively correlated with MYC, p65, and BCL2L1 (p < 0.01), while negatively correlated with infiltration levels of CD8+T cells." (PMID 38231305, 2024). "MYC and NCAPG2, key players in cancer research, are of paramount importance in unravelling the complexities of colorectal cancer." (PMID 38637125, 2024). "We demonstrated that STK16 promoted colorectal cancer progression by phosphorylating c-MYC at S452, leading to an upregulation of c-MYC expression." (PMID 38622518, 2024). "A phenoxy-N-phenylaniline derivative was shown to interfere with MYC/MAX dimerization, thereby efficiently inhibiting MYC in colorectal cancer cell lines." (PMID 36969025, 2023).
colorectal cancer (continued). "PDE4B modulates the expression of MYC that leads to low intracellular cAMP levels, activates AKT/mTOR signaling, and promotes cell survival in colorectal cancer." (PMID 36874096, 2023). "In studies on other types of cancer, such as in colorectal cancer and bladder cancer cell lines, BRD4-bound circRNA regulates MYC expression, and BRD4 bound the super-enhancer regulates expression levels of lncRNA PVT1 and MYC." (PMID 36895010, 2023). "Our findings shed light on the role of NEK8/MYC signaling in CRC progression, offering a novel and helpful target for colorectal cancer treatment." (PMID 37596667, 2023). "In colorectal cancer, the cellular inhibitor of PP2A—CIP2A protein regulates translation of the MYC gene mRNA and by increasing the level of MYC protein leads to carcinogenesis." (PMID 36769304, 2023). "An MYC target gene, PES1, has been shown to have links with chemoresistance in colorectal cancer cells." (PMID 37373047, 2023). "The CMS2 subtype accounts for 37% of colorectal cancer and is characterized by an activated WNT pathway and high MYC signaling." (PMID 37377612, 2023). "PTPN18 triggers MYC signaling by interacting with MYC and increases CDK4 protein expression in colorectal cancer." (PMID 36846716, 2023). "HIF2α enhances MYC function by stabilizing the MYC-MAX dimer in clear cell renal carcinoma cells and colorectal carcinoma cell lines." (PMID 37601651, 2023). "PDE4 is responsible for the degradation of cAMP, and MYC acts as a transcriptional activator of PDE4, maintaining a low level of cAMP in cells and promoting the survival of colorectal cancer cells." (PMID 35978822, 2022). "In the current study, we aimed to evaluate the expression as well as the possible relationship among MYC, PVT1, and CASC11 in colorectal cancer." (PMID 36052265, 2022). "The study on colorectal cancer revealed that LncRNA LINRIS enhanced the stability of IGF2BP2, which increased the binding of IGF2BP2 to m6A-modified MYC." (PMID 36358799, 2022). "Conditions prompting genetic testing in this group included essential thrombocythemia (CALR; JAK), colorectal cancer (MSH 2/6, MYC), Friedrich ataxia (FXN), and long QT syndrome (SNTA1)." (PMID 34515987, 2022). "Most driver genes were only found in single cancer types and represented key disease-specific drivers such as EGFR and TERT in glioma, MYC in BNHL, and APC in colorectal cancer." (PMID 35947558, 2022). "To elucidate the role of PVT1, CASC11, and MYC in CRC, we assessed the expression levels of these genes using qRT-PCR for cancerous and adjacent normal tissues from colorectal cancer patients." (PMID 36052265, 2022). "Several genes with high-frequency and important CNVs, namely, MYC, FGFR1, CCNE1, and CCND3 have been observed in lung and colorectal cancer samples." (PMID 35402275, 2022). "Accumulating evidence suggests that the PVT1 locus as an epigenetic enhancer in colorectal cancer (CRC) and it has a regulatory effect on regulating the expression of MYC." (PMID 35392800, 2022). "Additional evidence for this interaction stems from colorectal cancer studies where upregulation of RUNX3 by Bone Morphogenetic Protein (BMP) reduces c-MYC expression, thereby exerting c-MYC tumour-suppressor activity." (PMID 35069677, 2021). "Previous studies revealed that USP28 is required for the stability of oncoproteins such as c-MYC in colon cancer 37-39, and c-JUN and NOTCH in colorectal cancer." (PMID 33664871, 2021).
colorectal cancer (continued). "Some studies have noted that the MYC/MNX1-AS1/YB1 signaling pathway can drive proliferation and affect survival in colorectal cancer." (PMID 34394377, 2021). "This compound inhibited the expression of various Wnt target genes (such as MYC, AXIN2, and CD44) through conformational modification of TNIK and abrogated the stemness of colorectal cancer cells." (PMID 32429395, 2020). "For instance, colorectal cancer (CRC)-specific seRNA CCAT1-L is classified as a nuclear-retained lncRNA, and 3C analysis showed that CCAT1-L locates at 335 kb upstream of MYC promoter (MYC-335)." (PMID 32278350, 2020). "The stabilized PDCD6/c-Raf complex subsequently activates the Raf/MEK/ERK signaling pathway and regulates the downstream transcription factors including MYC and JUN, which resulting in colorectal cancer growth and progression." (PMID 32746883, 2020). "Detection of some genes such as c-MYC, KRAS, BRAF, PIK3CA, PTEN can be used as a predictor of colorectal cancer." (PMID 33014884, 2020). "We focused on the utility of the droplet digital polymerase chain reaction (ddPCR) for detecting c-MYC gene copy number (GCN) gain in cell-free plasma and tumor tissue of colorectal cancer (CRC) patients." (PMID 30733532, 2019). "In colorectal cancer cells, a study noted that CCAT1 was located within a super-enhancer and interacted with CTCF protein to maintain chromatin looping between the MYC promoter and its enhancers, resulting in elevated expression of MYC33." (PMID 30190462, 2018). "MiR-342 was shown to be a negative regulator of E2F1 affecting MYC expression in lung cancer cells and also negatively regulate FOXM1 and FOXQ1 expression in colorectal cancer cells." (PMID 29599914, 2018). "Recently, some driver proteins in these pathway, for example the MYC and EGFR antagonists, were also being developed as therapeutic agents for prostate and colorectal cancer." (PMID 30065750, 2018). "PCAT1 and CCAT1 have been identified as prognostic markers in prostate and colorectal cancers acting as transcriptional regulators of the genes BRCA2 and MYC respectively." (PMID 28945760, 2017). "In this study, we analysed GCN variation of the EGFR, HER2, c-MYC, and MET genes in 334 colorectal cancer tissue samples using silver-enhanced in situ hybridization (SISH)." (PMID 28764718, 2017). "We have recently shown that the integrin α1 protein and transcript (ITGA1) are present in a large proportion of colorectal cancers (CRC) and that their expression is controlled by the MYC oncogenic factor." (PMID 28933766, 2017). "Even though it was first reported in colorectal cancer, CCAT1 is involved in multiple malignancies based on its enhancer regulation of MYC." (PMID 29284497, 2017). "The purpose of this study was to explore gene copy number (GCN) variation of EGFR, HER2, c-MYC, and MET in patients with primary colorectal cancer (CRC)." (PMID 28764718, 2017). "Correlation between EGFR, AKT1, MYC, KRAS and SRC and, colorectal cancers separately or in combination with the other genes are studied and confirmed." (PMID 29511483, 2017). "On the contrary, MYC misregulation differed according to the malignancy type and only colorectal cancers (COAD and READ) showed a high frequency of MYC up-regulation." (PMID 27366943, 2016). "In colorectal cancer, TFAP4 was found to be required for MYC-induced EMT, migration, and invasion providing strong evidence for this transcription factor being a new regulator of EMT contributing directly to colorectal cancer metastasis." (PMID 27448979, 2016). "The copy number gain of ERBB2, RECQL4, and MYC oncogene and MAGEB family has been frequently reported in colorectal carcinoma, as shown in a recent review." (PMID 27481518, 2016).
colorectal cancer (continued). "These human colorectal carcinoma cell lines were established from tumour induced in mice by the SW613-S cell line, which contains the amplification of MYC in the form of dmins." (PMID 23821669, 2013). "In order to determine an involvement of c-MYC and SIRT1 in the tumorigenesis of the serrated route to colorectal cancer, we analyzed their expression in a well characterized collection of serrated polyps and carcinomas." (PMID 23045412, 2012). "In colorectal cancer, PTEN knockdown results in nuclear β-catenin accumulation and in increased expression of downstream proteins c-MYC and cycline D1." (PMID 22520842, 2012). "In colorectal cancer of the classical route SIRT1 is overexpressed, which correlates with high c-MYC expression." (PMID 23045412, 2012). "The increasing expressions with higher grades of malignancy suggest crucial functions for c-MYC and SIRT1 in the progression of serrated lesions to colorectal cancer." (PMID 23045412, 2012). "Taken together, we provide evidence that c-MYC and SIRT1 are crucially involved in the alternative, serrated pathway to colorectal cancer." (PMID 23045412, 2012). "To further investigate this phenomenon, we examined three diverse cancer cell lines that harbored MYC/PVT1 amplification and PVT1 translocations: COLO-320DM (colorectal cancer), SK-PN-DW (primitive neuroectodermal tumor (PNET)), and D458 (medulloblastoma (MB))." (PMID 40027648, 2025). "This hypothesis is supported by studies in other cancers, such as colorectal cancer, where EFTUD2 has been shown to influence c-MYC stability and contribute to chemoresistance." (PMID 40650074, 2025). "Furthermore, in breast and colorectal cancers, TPX2 has been identified as a MYC-cooperating oncogene that drives tumorigenesis." (PMID 40564876, 2025). "The protooncogene MYC was shown to be upregulated and CD117 was downregulated in colorectal cancer." (PMID 38255998, 2024). "Notably, the core genes (MYC, MAD2L1, CENPF, UBE2C, NUF2, NCAPG2) had differential expression in colorectal cancer samples in comparison to normal samples." (PMID 38637125, 2024). "After c-MYC is reduced, the expression of HK2, PFKM, PKM2 and LDHA in colon cancer cells is reduced, glycolysis is inhibited, and intracellular ATP is reduced, resulting in endoplasmic reticulum stress and immunogenic cell death in colorectal cancer cells." (PMID 39609317, 2024). "In colorectal cancer, lncRNA PVT1 has been reported to stabilize MYC protein." (PMID 39830506, 2024). "Elevated levels of MYC and NCAPG2 in colorectal cancer correlate with poorer prognosis." (PMID 38637125, 2024). "Moreover, IHC assays in colorectal cancer tissues demonstrated a positive correlation between STK16 and c-MYC expression levels." (PMID 38622518, 2024). "Furthermore, we generated four types of colorectal cancer cells stably expressing vector + c-MYC WT, STK16 + c-MYC WT, vector + c-MYC S452A, and STK16 + c-MYC S452A using lentivirus and the Crispr-Cas9 system." (PMID 38622518, 2024). "Interestingly, a feedforward loop between MYC and LARP1 was recently identified to promote tumorigenesis in colorectal cancer." (PMID 38067212, 2023). "Moreover, in colorectal cancer, CAD is regulated by MYC and when the metabolic reprogramming observed in cancer cells as a result of MYC activation is inhibited, cell growth is blocked by shutting down CAD and other enzymes of pyrimidine biosynthesis." (PMID 36295658, 2022). "Intriguingly, although MYC is overexpressed 5 to 400-fold in 70% of colorectal carcinoma (CRC) patients and 4 to 6-fold in 44% of hepatocellular carcinoma (HCC) patients, genetic amplification of MYC is only detected in 10% and 4% of CRC and HCC patients respectively." (PMID 34937878, 2022). "In contrast to what has been reported in breast and colorectal cancer cells, palbociclib induced a decrease in c-MYC expression, and no change in mTOR pathway activity, as assessed by p-S6 protein levels." (PMID 33572972, 2021).
colorectal cancer (continued). "For example, m6A modification stabilizes and promotes the expression of SOX2 through IGF2BP2-dependent pathways and increases the expression of its downstream targets (CCND1, MYC, and POU5F1), which in turn promotes the occurrence, invasion, and metastasis of colorectal cancer." (PMID 33926508, 2021). "In the case of both the MYC and EMT pathways, many studies have investigated their role in colorectal cancer." (PMID 34804112, 2021). "Indeed, colorectal cancer cell lines express 5–10 times more ITGA6A and MYC that their normal counterparts while the integrin α6Aβ4 was found to promote proliferation in colorectal cancer cells." (PMID 31877793, 2019). "An integrated data analysis showed that nearly all tumours displayed dysregulation of MYC transcriptional targets as a result of MYC activation by activated WNT signalling and/or dysregulation of TGF-β signalling, indicating an important role for MYC in colorectal cancer." (PMID 27325016, 2016). "Similarly, several cancer types including colorectal cancers, diffuse large B cell lymphoma, and multiple myeloma display increased POLRMT expression correlated with increased MYC expression in cancer cells compared to normal control cells." (PMID 27590350, 2016). "Indeed, MYC promotes CCAT1 transcription by binding to its promoter, and in colorectal cancer the L-isoform of CCAT1 has been shown to interact with the MYC promoter and distal upstream enhancer elements regulating MYC transcription." (PMID 27363682, 2016). "This region has not previously been studied as a long-range MYC control region, but has SE properties in colorectal carcinoma and diffuse large B cell lymphoma cell-lines." (PMID 27490482, 2016). "Using high-throughputscreening, we identify small molecule inhibitors of HUWE1, which inhibit MYC-dependenttransactivation in colorectal cancer cells, but not in stem and normal colon epithelial cells.Inhibition of HUWE1 stabilizes MIZ1." (PMID 25253726, 2014). "Furthermore, with higher grades of malignancy and invasiveness the expression of c-MYC and SIRT1 consistently increased, implicating a so far unrecognized role of c-MYC and SIRT1 in the tumorigenesis of the serrated route to colorectal cancer." (PMID 23045412, 2012). "Among the up-regulated genes in colorectal cancer, we found 14 genes involved in signal transduction (TDGF1 and ENC1), transcription (SOX9, MYC, and HGFR/MET), nuclear transport (NUP62, NUPL1, NUP155, KPNA2, RANBP5, CSE1L/CAS, NTF2, and RANBP1) and cellular transport (SLCO4A1)." (PMID 16919171, 2006). "Consequently, in colorectal cancer, sensitivity to ZKN-157 in cell lines and patient-derived organoids was restricted to the consensus molecular subtype 2 (CMS2) subtype that is distinguished by high MYC and WNT pathway activity." (PMID 37377612, 2023). "Our study suggested that MYC could bind to the promoter region of MTHFD2 and transcriptionally regulate MTHFD2 in NSCLC, consistent with previous experiments in acute myeloid leukemia and colorectal cancer." (PMID 36051358, 2022). "Furthermore, different genes are hypermethylated in cancers such as CDKN2A, hMLH1, and APC in colorectal cancer (CRC); p16INKa, RB1, and VHL1 in renal cell carcinoma; TET2, DNMT3B, IDH1, BRAF, and MYC in prostate cancer; and MGMT in colon, lung, lymphoid, and other tumors." (PMID 35327559, 2022).